ZEB2 (zinc finger E-box binding homeobox 2)
Diseases named in the same sentence as ZEB2 in open-access papers (continued):
Sharing a sentence is not in itself a finding about the gene and the disease.
tumor (continued). "In renal cancers, miR-192 acts as a tumor suppressor by targeting MDM2, ZEB2, and TYMS in renal cell carcinoma, thereby reducing migration and invasion." (PMID 40087755, 2025). "In both KP.SIY models, Zeb2 knockout significantly suppressed the number of lung tumor-reactive CD8+ cells on days 7, 10, 13, and 16 post-tumor cell inoculation." (PMID 41203628, 2025). "Combined expression of WNT ligands (WNT3A, WNT4, WNT7B, WNT9A, WNT10A, WNT11) in BRCA patient tumours has a positive correlation (R = 0.27, p value = 0) with the combined expression of key EMT-inducing transcription factors SNAI1, SNAI2, ZEB1, ZEB2 and TWIST1." (PMID 38678032, 2024). "Regarding the expression of transcription factor genes, the expression was higher in EPCAM-positive CTCs (CDH1, ZEB1, ZEB2) and in EPCAM-positive primary tumor cells (CDH1, SNAIL1, SNAIL2, ZEB2) compared to EPCAM-negative CTCs and tumor cells." (PMID 39456890, 2024). "The expression of E‐cadherin is essential for the tumor‐initiating capacity, while mesenchymal features with high ZEB1, ZEB2, and SNAIL can impair this capacity." (PMID 39092293, 2024). "Analysis of the DEGs in TCGA tumours revealed that the miR-18a/low tumours expressed high levels of EMT master regulators-ZEB1 and ZEB2 and Matrix metalloproteinases, MMP2, MMP3, MMP10, MMP11, MMP13 and MMP17 (p < 0.05)." (PMID 38786043, 2024). "In NSCLC tissues and cell lines, E2F1 is notably upregulated and controls ZEB2 expression via an E2F1 binding site on the ZEB2 promoter, ultimately driving EMT and enhancing tumor invasion and metastasis." (PMID 39737184, 2024). "It acts as a tumor suppressor by targeting key molecules involved in the EMT process, such as ZEB2 and Six1." (PMID 39199587, 2024). "MiR-200c-3p is a well-known tumor suppressor miRNA that inhibits tumor progression and metastasis in breast cancer by downregulating ZEB1 and ZEB2." (PMID 39372872, 2024). "ZEB2 is a DNA-binding transcription factor that is mainly involved in EMT and plays a pivotal role in drug resistance, survival, tumor recurrence, and metastasis." (PMID 37345024, 2023). "Among these genes, ZEB2 was reported to mediate crosstalk between TGFβ signaling and the EMT pathway, which further emphasizes the tumor‐promoting activity of TGFβ signaling and the therapeutic role of TGFβ blockade in the SCS2 subtype." (PMID 36349418, 2023). "In melanocytes, a shift from ZEB2 to ZEB1 was previously shown to modulate the balance between cell differentiation and proliferation and to thereby drive tumor initiation and secondary site colonization." (PMID 36765930, 2023). "ZEB2 upregulates MMP activity and reduces E-cadherin epithelial marker and intercellular adhesion, thus facilitating tumor cell invasion." (PMID 37854681, 2023). "It is known that microRNA-200 family miRNAs target genes ZEB1 and ZEB2, which both are involved in EMT and tumour metastasis." (PMID 37705830, 2023). "PTEN, for example, is one of the most well-known tumor suppressors, and ZEB1 and ZEB2, the most important genes involved in EMT, are at the top of the table." (PMID 37854681, 2023). "Particularly, the CMS4 categorization was linked to an EMT signature that included a notable decrease in the microRNAs that control tumor suppression via ZEB1 and ZEB2." (PMID 37834263, 2023). "Crucially, C3AR1 is positively correlated with 18 tumor metastasis related genes including FN1, SNAI2, and ZEB2." (PMID 37005667, 2023). "Although TGF-signalling is associated with cancer suppression in the early stages of tumour development, in late-stage tumours it exerts oncogenic function partially through inducing EMT-related factors such as Snail, Slug, ZEB1, ZEB2 and LEF1." (PMID 37239035, 2023). "Interestingly, when the authors introduced a double knockout of Zeb2 and Zeb1 in this same MLL-AF9 model they did not observe any further delay in tumor onset suggesting that Zeb1 loss was could not compound the effect of Zeb2 loss alone." (PMID 37600794, 2023).
tumor (continued). "ZEB2 (zinc finger E-box binding homeobox 2) usually functions as a repressor of DNA transcription in the nucleus and plays a crucial role in the EMT of tumor cells." (PMID 35600868, 2022). "Members of the miR-200 family act as tumour-suppressive miRNAs, enhancing the expression of E-cadherin and suppressing the expression of ZEB1 and ZEB2." (PMID 36499447, 2022). "The role of miR-200 has previously been reported as a tumor suppressor factor for the inhibition of the EMT process and tumor growth of GC through targeting ZEB1 and ZEB2." (PMID 34923813, 2022). "miR-200c acts as a tumor suppressor that inhibits tumor growth and blocks EMT by targeting ZEB1 and ZEB2." (PMID 35406505, 2022). "On the contrary, miRNAs-200c and 205 appeared as downregulated in OSCC cell lines and tumour samples (the former) and in OSCC cell lines (the latter), whereas their targets, ZEB1 (for miRNA-200c) and ZEB1 and ZEB2 (for miRNA-205), showed to be upregulated." (PMID 34564679, 2022). "Accumulating evidence has shown that ZEB2 has a major role in the EMT process, including growth, differentiation, resistance to therapy and apoptosis, metastatic potential, and tumor recurrence." (PMID 36313570, 2022). "In OV, ZEB2 is positively correlated with CD8+T cells, neutrophils, macrophages, and dendritic cell invasion; and ZEB2 is negatively correlated with tumor-infiltrating B cells." (PMID 35723302, 2022). "miR-200a, a family of tumor suppressor miRNAs, is downregulated in TNBC and maintains a stable epithelial phenotype by directly targeting the E-cadherin repressors ZEB1 and ZEB2, thereby significantly inhibiting EMT and metastasis." (PMID 36052258, 2022). "Fourth, the characteristic hypoxia of co-opted tumors generates high levels of HIF1α, a known inducer of the EMT transcription factor Zinc finger E-box binding homeobox 2 (ZEB2) that suppresses ephrinB2, thereby enhancing tumor invasiveness." (PMID 36119528, 2022). "Mechanistically, transcriptional repression of E-cadherin by multiple downstream transcription factors, such as Snail, Slug, DEF-1/ZEB-1, SIP-1/ZEB-2 and Twist, triggers EMT-mediated tumor progression." (PMID 35713314, 2022). "It was proven that miR-769-3p blocks the Wnt/β-catenin pathway by targeting zinc finger E-box-binding homeobox 2 (ZEB2), thereby suppressing tumor growth." (PMID 36230935, 2022). "In support of this, SRC activation was strongly correlated with the PC1 and EMT signatures and the EMT genes (e.g. ZEB2, TWIST1) that are known to promote migration, invasion and metastasis and to induce tumor cells to acquire stem cell characteristics." (PMID 35272617, 2022). "Moreover, based on the expression of EMT hallmark genes including SNAI2, N-cadherin, Vimentin, ZEB1, ZEB2, SNAI1, Fibronectin, TWIST1 and E-cadherin, we found that patients with high risk score distinctly exhibited a mesenchymal phenotype, suggesting a higher tumor malignancy." (PMID 36505846, 2022). "Overexpression of other EMT-TFs such as ZEB2, TWIST1, and SNAI1 similarly reduced tumor growth and metastatic load arguing that different EMP states induced by distinct means in MCF-7 cells neither favor tumor progression nor metastasis." (PMID 36008376, 2022). "To further characterize the role of EMT in tumor progression, we analyzed the expression of EMT markers ZEB2, SNAI2, and β-catenin in an experimental 3D tumor stroma." (PMID 36552039, 2022). "Our results suggest that decreased expression of miR-200b, ZEB2 and PTPN13 is involved in local tumour spread of CRC, particularly in serosal invasion (pT4a)." (PMID 36140249, 2022). "There are many transcription factors involved in the occurrence of tumor EMT, such as Snail/Slug family, Twist, EF1/ZEB1, SIP1/ZEB2 and E12/E47." (PMID 34517345, 2021). "Compared to the bulk of the tumor, tumor budding cells in PDAC are reported to express increased levels of the EMT-related transcription factors ZEB1 and ZEB2 and decreased expression of the cell-to-cell adhesion protein, E-cadherin." (PMID 33806316, 2021).
tumor (continued). "Xenograft tumor of HCT 116 showed an increased expression of neuronal genes MAP2 and SYN1, neural stemness genes CDH2, MSI1, NCAM1, SOX2/9, VIM and ZEB2, and genes for mesodermal and endodermal tissues (ACP5, AFP, DESMIN, HNF4A and KRT8)." (PMID 33468253, 2021). "Gene expression comparison between U-118 MG cells and the tumor showed an increased expression of neuronal and neural stemness genes MAP2, NEUN, ROBO2, PAX6, ZIC1, ZEB2, as well as MYC and OCT4 in tumor." (PMID 33468253, 2021). "Several studies show the tumor-suppressive role of miR-200b in PC by targeting different genes, e.g., ZEB1, ZEB2 and Bmi-1." (PMID 33331954, 2021). "ZEB2 was elevated in ascitic cells, while the changes in ZEB1, Snail and Twist1 in ascites and primary tumours were mild." (PMID 34211089, 2021). "Compared to those in OSE controls, ZEB2, N-cad and Bax were higher in HGSOC tumour tissues, while E-cad and Bcl2 were lower, and these changes were amplified with progressing stage." (PMID 34211089, 2021). "Taken together, miR-6734-3p played an anti-tumor role to hinder cancer development and enhanced the cytotoxic effects of cisplatin treatment on NSCLC cells by downregulating ZEB2." (PMID 34107856, 2021). "In lymph node metastases compared to the invasive front of the tumor, ONECUT2 and SOX2 were down-regulated, while PTPN13, TGFB2, ZEB2, RND3 and CDKN1B were up-regulated." (PMID 34046357, 2021). "In this study, we investigated and validated for the first time, the prognostic value of ZEB2 expression in a cohort CRC patients, who received adjuvant FOLFOX therapy after surgical resection of the primary tumour." (PMID 33931939, 2021). "Taken together, we identify ZEB1 and ZEB2 as EMT genes correlated with PRRX1 and assumingly acting with it to influence tumour characteristics." (PMID 34496784, 2021). "Recently, the five member miR-200 family (miR-141, -200a, -200b, -200c, and -429) and miR-205 have been identified as EMT-suppressive or ‘tumor-suppressive’ miRNAs directly targeting ZEB1 and ZEB2." (PMID 34638432, 2021). "It is well known that SNAI1, SNAI2, ZEB1, ZEB2, TWIST1 and TWIST2 are key transcription factors involved in EMT in various types of cancers, and they contribute to enhanced tumour cell migration, invasion and metastasis capacities." (PMID 32488136, 2020). "In prostate cancer, miR-205 was demonstrated to act as a tumor-suppressor by repressing the expression of factors (N-chimerin, E2F1, E2F5, ZEB2, and protein kinase Cε) involved in EMT, cell motility and invasion." (PMID 33191398, 2020). "Alternatively, miR-200 is frequently downregulated in human tumours resulting in EMT induction and leads to suppression of epithelial genes mediated by its targets ZEB transcription factors (ZEB1 and ZEB2)." (PMID 32577155, 2020). "In parallel, chemotherapy treatment of tumor xenografts induced the prevalence of QCSCs with a stemness/EMT phenotype and activation of the ZEB2/pCRAF/pASK1 axis, resulting in a chemotherapy-unresponsive state." (PMID 31910865, 2020). "ZEB2 plays a pivotal part in EMT and invasion of tumor cells, and can transform non-invasive cancer cells into cancer stem cells." (PMID 32391554, 2020). "Tumour budding cells in PDAC have been observed with increased levels of ZEB1 and ZEB2, and reduced levels of E-cadherin and β-catenin, indicative of EMP mediated local invasion." (PMID 31703358, 2019). "miR-101 has been reported to act as a tumor suppressor by targeting CDH1 inhibitors, such as ZEB1/ZEB2 and EZH2 in different tumors, including GC." (PMID 31509966, 2019). "Down-regulation of the miR-200 family at the invasive front in comparison to the central part of tumour was observed as well as a correlation of expression of miR-200b, CDKN1B, ONECUT2 and ZEB2 expression to nodal metastases." (PMID 31623346, 2019).
tumor (continued). "Previous studies showed that ZEB1/ZEB2 and miR-200 family negatively regulate each other, which has important implication for EMT and tumor metastasis." (PMID 31263239, 2019). "Down-regulating the expression of miR-200a promote tumor growth and EMT via targeting E-cadherin repressors ZEB1/ZEB2 in Wnt/β-catenin pathway." (PMID 31652445, 2019). "In conclusion, we demonstrate that, besides its role in cancer cell invasion, ZEB2 directly promotes CTC survival and tumor angiogenesis through cooperation with Sp1." (PMID 29416649, 2018). "When expression of this family of miRNAs is restored in these malignancies, the miRNAs act as tumor supressors repressing the oncogenes TYMS, ZEB2, and MDM223,28,29." (PMID 30038317, 2018). "Tumor miR-200b expression was significantly greater in LC-COPD than in LC patients, while that of its downstream markers ETS-1 and ZEB-2 was significantly reduced." (PMID 29371906, 2018). "The most characteristic feature of the Mes-like group of tumors is tumor cell expression of VIM and ZEB2, markers for a mesenchymal phenotype." (PMID 29487377, 2018). "Both miR-30a-5p and -3p showed the capacity of targeting ZEB2, a transcription factor involved in epithelial–mesenchymal transition (EMT), tumor cell migration and drug resistance." (PMID 29666469, 2018). "Non-tumor lung expression of miR-200b also significantly increased in LC-COPD compared to LC patients, and only the expression of ZEB-2 significantly decreased." (PMID 29371906, 2018). "In the mouse xenograft models, the mRNA level of ZEB2, vimentin and N-cadherin was downregulated while E-cadherin was up-regulated in the DLX6-AS1 knock-down group with reduced tumor size and suppressed tumor metastasis." (PMID 30250401, 2018). "The ZEB1 (log 2fc=−2.28) and ZEB2 (log 2fc=−2.3) transcripts are also significantly overexpressed, implying induction of the EMT in the responder tumor." (PMID 28594404, 2017). "The reduction of miR-9-5p, miR-144, miR-145 and miR-229 leads to tumor progression through the miR-9-5p/POU2F1, miR-144/c-Met, miR-145/ZEB2 and miR-229/VEGFA signaling pathway." (PMID 28548946, 2017). "ZEB2 plays a key role in the TGF-β signaling cascade and promotes tumor cell invasion and metastasis." (PMID 27924058, 2017). "MiR-141 is reported to function as a tumor suppressor and inhibit EMT and metastasis of tumor cells by targeting ZEB2." (PMID 26790956, 2016). "In order to clarify the relationship between MAZ, ZEB1 and ZEB2 in HCC, we detected their expression in 75 pairs of HCC and adjacent non-tumor tissues." (PMID 27861158, 2016). "We detected the expression of ZEB1 and ZEB2 in the 75 pairs of HCC and adjacent non-tumor tissues that MAZ expression had been measured by IHC." (PMID 27861158, 2016). "Knocking down ZEB2 significantly suppressed the percentage of SP cells and DDP resistance by reducing the expression of tumor stemness factors including BMI1, SOX2, NANOG, and OCT4." (PMID 27589832, 2016). "Of note, tumor buds show strong expression of the epithelial-mesenchymal transition markers ZEB1 and ZEB2." (PMID 26716653, 2016). "Several transcription factors, including Snail, Slug, Twist, ZEB1, and ZEB2, have been identified as inducers of EMT and tumor metastasis." (PMID 27549611, 2016). "miR-203 exerted these effects by targeting ZEB2 and downstream epithelial-mesenchymal transition (EMT) and tumor stemness signals." (PMID 27589832, 2016). "In this study, we investigated the roles of miR-203 and ZEB2 on NPC cell migration, invasion, tumor stemness and chemotherapy resistance." (PMID 27589832, 2016).
tumor (continued). "Consistent with the tumor suppressor activities of E-cadherin, downregulation/lack of E-cadherin expression due to the high levels of its transcriptional repressors Snail, Twist and ZEB-2 has been associated with the migratory and invasive properties of ES-2 and other OVCA cells." (PMID 27144941, 2016). "Protein levels of ZEB2, BMI1, OCT4, and NANOG were decreased in tumor spheres compared to parental NPC cells." (PMID 27589832, 2016). "In this study, we used immunohistochemistry to study the expression of a panel of transcription factors (TWIST1, SNAI1/2, ZEB1 and ZEB2) and other genes intimately related to EMT (CDH1 and LAMC2) at the invasive tumor front of OSCC tissues." (PMID 26214683, 2015). "Zeb2 as a key transcription factor inducing EMT occurrence, plays a vital role in a variety of tumor cells." (PMID 25460509, 2015). "As a result, a strong positive correlation (Pearson, r=0,787 was seen between Zeb2 and Il7r mRNA expression levels in our mouse and human (Pearson, r=0.735) immature/ETP-ALL tumours." (PMID 25565005, 2015). "Expression of SNAI1/2, ZEB2 and TWIST1 were observed in the nucleus as well as the cytoplasm of epithelial cells, however, only nuclear staining in normal and tumor epithelial cells was evaluated as these proteins are expected to regulate transcription." (PMID 26214683, 2015). "mir-200 family plays critical roles in tumor development and progression through inhibiting EMT and suppressing tumor invasion by directly repressing the transcription factors ZEB1 and ZEB2." (PMID 25972084, 2015). "We then detected the expression of ZEB2, miR-200c and MALAT1 in 40 tumor specimens and their paired normal adjacent tissues by real-time PCR." (PMID 26461224, 2015). "LncRNA-ATB promotes and sustains EMT and tumor invasion via two mechanisms: on one hand, lncRNA-ATB up-regulates Zeb1 and Zeb2 by competitively binding the miR-200 family, which targets Zeb1 and Zeb2, thus acting as a ceRNA." (PMID 25428918, 2014). "MiR-200s have been demonstrated to act as a tumor suppressor by suppressing Zinc-finger enhancing binding transcription factors (ZEB1 and ZEB2) to increase the E-cadherin in cancer cells." (PMID 24918286, 2014). "ZEB1 and ZEB2, members of the ZEB family, have been shown to induce EMT through repression of E-cadherin and to promote tumor progression and metastatic spread." (PMID 24677166, 2014). "Members of the miR-200 family have been found to act as tumor suppressor miRNAs that inhibit EMT by down regulating the expression of ZEB1 and ZEB2." (PMID 24967704, 2014). "Since MiR-200s have been demonstrated to act as a tumor suppressor by suppressing Zinc-finger enhancing binding transcription factors (ZEB1 and ZEB2) to increase the E-cadherin in cancer cells, we measured ZEB1 levels from the samples of reporter assays." (PMID 24918286, 2014). "Once this process is under way in a tumor, it is typical to find a coordinated alteration in the expression of all these genes: the expression of ZEB1, ZEB2, VIM, and SNAI1 is upregulated, while the expression of CDH1 is downregulated." (PMID 25157365, 2014). "During tissue remodelling or tumor progression, several transcriptional repressors, such as Snail, Slug, ZEB1, ZEB2 and Twist1, can down-regulate E-cadherin expression leading to a reduction of cell-cell adhesion and promotion of EMT and cell motility." (PMID 24967704, 2014). "Studies have shown that by targeting the transcriptional repressors of E-cadherin, ZEB1 and ZEB2, the miR-200 family is involved in epithelial-to-mesenchymal transition (EMT) and tumor invasion." (PMID 24223734, 2013). "They target ZEB1 and ZEB2, transcriptional repressors of E-cadherin, and thereby inhibit EMT and tumor invasion." (PMID 23741524, 2013). "A Cox proportional hazards regression analysis demonstrated a significant impact of prognostic features (i.e., tumor size, TNM stage, Fuhrman grade and ZEB2 expression) on the patient survival rates (P<0.05)." (PMID 23658743, 2013).